IL10 (interleukin 10)
Diseases named in the same sentence as IL10 in open-access papers (continued):
Sharing a sentence is not in itself a finding about the gene and the disease.
melanoma (continued). "In contrast with the A-SMase-mediated inhibitory effect on proinflammatory cytokines we also found that low A-SMase in melanoma accounts for the high expression of the anti-inflammatory cytokines IL-10 and TGF-β1." (PMID 26101462, 2015). "In this regard, here we showed that the expression of IL-10Rα is crucial for the melanoma cell responsiveness to IL-10." (PMID 26631117, 2015). "Those β-catenin-overexpressed melanoma cells can also inhibit IFN-γ production by melanoma-specific CTLs in an IL-10-independent manner and is more resistant to CTL lysis in vitro and in vivo." (PMID 26652024, 2015). "Dendritic cells from IL-10-expressing melanoma tumors and IL-10-exposed immature monocyte-derived dendritic cells were then also shown to be tolerogenic." (PMID 24550907, 2014). "In a mouse model of melanoma, tumors overexpressing IL-10 present a higher tumor growth mediated by an increase in tumor cell proliferation, angiogenesis, and immune evasion." (PMID 24901008, 2014). "In a mouse model of B16 melanoma, the induction of IL-10 has also been shown to limit the anti-tumor effects of TLR2 agonist Pam2 lipopeptide." (PMID 24624132, 2014). "Type II cytokines such as IL-6, TNF-α, IFN-γ and IL-10 have also been shown to be important regulators of melanoma immune tolerance and escape." (PMID 24457057, 2014). "In melanoma, production of B cells secreting inhibitory IgG4 is stimulated by the tumor secreted IL-10 and IL-4." (PMID 24743024, 2014). "In a separate study, IL-10 expression in the melanoma line A375 was found to be induced by TGF-β, an effect that was mediated by cross-talk between the Smad, PI3K/AKT, and MAPK pathways." (PMID 24194739, 2013). "When we studied the expression of IL-10 in melanoma cell lines with measured expression of the TM protein of HERV-K, no IL-10 release was detected in the supernatant (unpublished)." (PMID 23950929, 2013). "It has been reported that IL-10 can be secreted by tumor cells and high IL-10 levels were observed in areas of spontaneous regression of primary melanoma." (PMID 24358317, 2013). "These are further supported by human studies in Hodgkin’s lymphoma, B cell lymphoma, melanoma, and hepatocellular carcinoma, where elevated serum IL-10 levels correlate with poor survival." (PMID 23755052, 2013). "Culture supernatant of human melanoma cells with accumulated β-catenin-induced high IL-10- and low IL-12-producing DCs in an IL-10 dependent manner." (PMID 23755373, 2013). "To evidence a possible correlation between IL-10 and IL-27 expression in melanoma lesions, we analyzed by immunohistochemistry IL-10 expression in 43 cases of primary cutaneous or metastatic melanoma." (PMID 24130734, 2013). "In vitro studies have shown that IL-10 treatment can convert different types of tumor cells, such as melanoma and lymphoma, to a CTL-resistant phenotype by decreasing the expression of HLA class I molecules on their surface." (PMID 23533029, 2013). "A previous study reported the effect of IL-10 on tumour growth in a mouse melanoma model and the induction of cell proliferation, either through autocrine stimulation of tumour cells or just through depression of the immune system." (PMID 22220169, 2012). "Ferritin released by melanoma was reported to induce IL10 production of lymphocytes and suppress immune responses." (PMID 22272696, 2012). "We observed many similarities to the immunosuppressive state present in melanoma patients, that is, functional impairment of T lymphocytes, increased numbers of Tregs, and strong expression of IL-10 and TGF-β1 in tumor-draining lymph nodes." (PMID 22674057, 2012). "Although IL-10 is considered to an anti-inflammatory cytokine, IL-10 can function as a growth factor to promote melanoma cell proliferation or possess an anti-apoptotic effect in lung cancer cells." (PMID 21897855, 2011). "IL-10 induces decreased MICA expression on melanoma cells in an autocrine loop and blocks the antitumor functions of DCs and NK cells." (PMID 22046194, 2011).
melanoma (continued). "The production of the immunosuppressive cytokine IL-10 by tumor cells themselves or by tumor-infiltrating immune cells is well known for malignant melanoma and other tumor entities." (PMID 21818385, 2011). "In melanoma cells increased elevated levels of interleukin 10 (IL-10) resulted in decreased cytosolic AUF1 levels as compared with normal melanocytes." (PMID 21835052, 2011). "Another study investigating the role of Stat3 in immune evasion in human melanoma cells, has reported that Stat3 siRNA decreased the mRNA expression of IL-6, IL-10 and VEGF." (PMID 21122157, 2010). "Cytokine production (IFN-γ, IL-10) by TyrTCR-transduced cells was also detected following co-culture with a melanoma tumor cell line expressing tyrosinase naturally processed and presented in the context of HLA-A*0201 (data not shown)." (PMID 20668510, 2010). "Different studies have reported increased IL-10 serum levels in patients with melanoma and other solid tumors, as well as expression of IL-10 by tumor cells." (PMID 20525400, 2010). "In these SLN the expression of IDO and IL-10 was found to be highest in SLN that were infiltrated with melanoma cells." (PMID 19604349, 2009). "Higher levels of IL-10 have been found in metastitic melanoma patients with respect to healthy donors." (PMID 17953739, 2007). "Proposed mechanisms for melanoma-derived immunosuppression include the secretion of TGFβ, IL-10 and IDO, which have been found in patients' blood, primary melanomas and sentinel lymph nodes (SLN)." (PMID 17565341, 2007). "We found that expression of IDO and interleukin 10 (IL-10) increased with melanoma progression, with the highest concentration in positive SLN." (PMID 17565341, 2007). "Serum soluble interleukin-2 receptor (sIL-2R), intercellular adhesion molecule-1 (sICAM-1) and interleukin-10 (IL-10) have each been reported as useful markers for melanoma progression." (PMID 10970683, 2000). "Interleukin 10 (IL-10) is an immunosuppressive factor and has been detected in tumour cell cultures of renal cell carcinoma and of malignant melanoma." (PMID 10098756, 1999). "Our data indicate that B7.1- and B7.2-transduced melanoma cells trigger lymphocytic proliferation with transcription of IL-10, IL-2 and IFN-gamma." (PMID 9652756, 1998). "After co-incubation of transduced melanoma cells with PBMCs, high levels of IL-10 were detectable in the supernatant." (PMID 9652756, 1998). "The expression of interleukin 10 (IL-10) mRNA in human malignant melanoma was investigated by reverse transcriptase polymerase chain reaction analysis." (PMID 7981073, 1994). "Selective expression of IL-10 mRNA in tissues of primary melanomas and melanoma metastases was found in comparison with normal skin." (PMID 7981073, 1994). "Melanoma patients showed more variable IL-10 trends, which may indicate heterogeneous regulatory immune responses, including possible immune evasion via T-cell apoptosis or downregulation of antigen presentation on dendritic cells." (PMID 41020868, 2025). "Regulatory IL-10-expressing plasmablasts in melanoma may thus serve as one potential source of IL-10, contributing to impaired antitumor activity, in part by upregulating IgG4." (PMID 40449958, 2025). "Moreover, we show that S3QEL 1.2 treatment decreases melanoma progression and improves the survival of mice in vivo, impairing the production of IL-10 by macrophages in the tumor microenvironment (TME)." (PMID 39841829, 2025). "Notably, serum levels of IL-10 and IL-17 in these patients are frequently significantly elevated, with serum IL-10 also serving as a potential predictor for melanoma recurrence." (PMID 40936907, 2025). "Interestingly, in vitro and in vivo experiments have validated that DHA reduces the expression of IL-10 and IL-6 proteins in melanoma and inhibits the phosphorylation of STAT3 to induce mitochondrial apoptosis." (PMID 41160271, 2025).
melanoma (continued). "Next, we investigated whether the LPA-LPAR1-DR6 axis and subsequent IL-10 release affect the expression of HLA-DR in human melanoma." (PMID 39187677, 2025). "This prospective single-center study examined associations between serum cytokines—TNF-α, IL-2, and IL-10—and outcomes in stage IV non-small cell lung cancer (NSCLC, n = 43) and melanoma (n = 15) patients treated with Nivolumab at the Oncology Institute in Cluj-Napoca, Romania." (PMID 41020868, 2025). "When melanoma cells engineered to overexpress IL-10 were implanted into immunocompetent hosts, tumorigenicity was diminished, and tumor eradication was directly correlated with IL-10 secretion levels." (PMID 40149345, 2025). "Several investigators suggest that some DN T cells may lack effector or cytotoxic functions, as observed in glioma and melanoma tissues TIME where they secreted immunosuppressive cytokine IL-10." (PMID 40075642, 2025). "Even certain malignant cells (melanoma, colon, and breast carcinoma) secrete IL-10." (PMID 40283387, 2025). "In clinical studies, IL-10 expression and production correlate with melanoma progression." (PMID 39187677, 2025). "IL-10 promotes melanoma growth by stimulating angiogenesis and immunosuppression in mice." (PMID 40469178, 2025). "Moreover, among the secreted cytokines for TIL-P generated in response to the melanoma cell line, IL-10 secretion was among the cytokines increased for TIL-P KIF-P2 compared to KIF-sc1." (PMID 39627205, 2024). "Melanoma exosomes have been shown to induce a spectrum of macrophage phenotypes secreting a variety of anti-inflammatory (IL-4, IL-10, IL-11, and IL-13) but also pro-inflammatory (TNF-α, IL-12B, IL-1β, IL-6, iNOS, and CCL22) factors, reflecting the spectrum of phenotypes detected in the TME." (PMID 38533720, 2024). "Likewise, small fold changes in IL-8 and IL-10 mRNA expression following dedifferentiation in melanoma cells have been reported." (PMID 39736644, 2024). "Despite the therapeutic efficacy demonstrated by PEGylated human IL-10 (pegilodecakin) in certain solid tumors like renal cell carcinoma and melanoma, its effects on patients with MA remain unclear." (PMID 38279997, 2024). "IL-10 has been implicated in driving tumor associated macrophage (TAM) polarization and has been linked to increased myeloid derived suppressor cell (MDSC) infiltration in melanoma." (PMID 39736644, 2024). "In addition, whereas the antitumor cytokines, like IFN-γ and TNF-α, in melanoma tissues increased, both IL-4 and IL-10 (pro-tumor cytokines) levels decreased at the end of the indicated treatment." (PMID 38491004, 2024). "Interestingly, the ability of B-1 cells to secrete IL-10 increases after being co-cultured with B16F10 melanoma cells or tumor-conditioned medium." (PMID 38629061, 2024). "Moreover, melanoma cells have been shown to release immunosuppressive cytokines, including IL-10 and TGF-beta." (PMID 38791968, 2024). "In addition, a separate melanoma study concluded that tumoral expression of CD200 similarly alters the tumor microenvironment by inhibiting IL-10 production from TAMCs." (PMID 38137547, 2023). "The proposed impact on T and NK cells by LOAd732 was evaluated in this study in human in vitro models and under suppressive conditions mimicking the TME by exposure to TGF-β1 and IL-10, which are two immunosuppressive factors overexpressed in malignant melanoma." (PMID 37501121, 2023). "Cytokines such as IL-4, IL-13, TGFβ, and IL-10 were most probably present in the melanoma-microglia interface and could have provided a variety of signals that led to divergent M1/M2 phenotypes." (PMID 37296634, 2023). "Surprisingly, IL-10/Fc treatment effectively controlled the growth of murine melanoma." (PMID 37398660, 2023). "However, several studies have shown a direct correlation between IL-10 and poor prognosis in melanoma, lung cancer, T/NK lymphoma and HNSCC." (PMID 37958430, 2023).
melanoma (continued). "Increased production of IL-10 has been observed in patients with melanoma and several types of lymphoma, and it is thought that it may affect the development of this type of malignancy." (PMID 37687297, 2023). "Importantly, dihydroartemisinin-mediated decrease of IL-10 and IL-6 in melanoma inhibited Treg polarization and infiltration in the TME." (PMID 36700235, 2022). "Both IL-10 and ANGPT2 are contained in transcriptional signatures associated with resistance against anti-PD-1 antibodies in melanoma patients, indicating that they rapidly act on the immune regulatory mechanism and can promote immune escape and, ultimately, tumor growth." (PMID 35681453, 2022). "The group also found that IL-6 may play a role in the stimulation of IL-10 production in melanoma cells." (PMID 35495152, 2022). "Interleukin-4 and 13 signaling, thyroid cancer, pathways in cancer, signaling by interleukin, interleukin-10 signaling, melanogenesis, melanin biosynthesis, and tyrosine metabolism might be the key to treating melanoma." (PMID 36185647, 2022). "Enhanced IL-10 expression has also been reported in melanoma cells co-cultured with B cells." (PMID 35255925, 2022). "According to other studies, IL-10 may also promote the development of glioma, lung cancer, squamous cell carcinoma of the esophagus, melanoma, and cervical cancer." (PMID 36009467, 2022). "Considering the suppressive role of IL-10 and Treg cells, these features could explain the inability of AIRmax to maintain cytotoxic activity when challenged with melanoma cells, and consequently, the higher incidence of primary tumors in animals." (PMID 35265317, 2022). "Further evidence that the production of HMGB1/RAGE-dependent IL-10 by macrophages promotes melanoma growth has come from a human melanoma tissue study, in which high infiltration of IL-10-producing macrophages was detected in melanoma tissue with a high expression of HMGB1." (PMID 36012593, 2022). "Our data indicate that MAF-induced IL-10 production in macrophages may contribute to melanoma aggressiveness, and targeting the cyclooxygenase and indoleamine 2,3-dioxygenase pathways may abolish MAF–macrophage interactions." (PMID 34944793, 2021). "Interestingly, melanoma-derived MAFs from tumors thicker than 2 mm provoked a markedly higher IL-10 output in THP-1 macrophages as compared to thinner melanomas less than 2 mm deep." (PMID 34944793, 2021). "Gray showed that melanoma cells secreting FTH1 could activate Tregs to produce interleukin-10 and suppress the immune response in vitro." (PMID 33864445, 2021). "Finally, we treated melanoma cells with dacarbazine, an alkylating chemotherapeutic agent, and found that drug-treated primary melanoma cells magnified the IL-10 elevating effect of MAFs on THP-1 cells." (PMID 34944793, 2021). "Besides, other immunomodulatory molecules, TLR, TNFα and IL-10 are also appealing for potential combination with ICBs to treat melanoma." (PMID 34924562, 2021). "Furthermore, circulating cytokine profiling highlighted a significant increase in IL-8 and IL-10 levels after treatment, mainly in melanoma patients." (PMID 34777395, 2021). "Moreover, IL10 was shown to exert antitumoral activity in gliomas, melanomas, and breast and ovarian carcinomas." (PMID 33579265, 2021). "IL-10+ B cells were also present in all 36 primary melanoma samples (100%)." (PMID 34359321, 2021). "Anti-IL-10 in combination with classical therapies in CLL could be beneficial as shown in other diseases such as leukaemia or melanoma." (PMID 35008174, 2021). "Furthermore, DHA enhances the killing effect of CTLs to mouse melanoma by reducing IL-10 content and the number of Treg in tumor microenvironment." (PMID 34692496, 2021). "Furthermore, flow cytometric analysis demonstrated that STAT3 inhibitor with PD-1 treatment weakened the secretion of TGF-β and IL-10 on Treg cells compared to anti-PD-1-treated melanoma mice, implying an enhanced anti-tumor immunity." (PMID 33936081, 2021).
melanoma (continued). "Melanoma cells have also acquired mechanisms to subvert the immune-stimulatory functions of pDCs, such as secrete immunosuppressive cytokines, including IL-10, TGF-β and PGE2, to suppress the expression level of TLR7/9 and IRF7, resulting in pDCs producing only a small amount of I-IFN." (PMID 34737750, 2021). "Interestingly, the gene expression levels of CD33, a marker of myeloid-derived suppressor cells (MDSCs), and IL-10, which is mainly secreted by regulatory T cells (Tregs), were higher in MAP2K1/2-mutated melanoma, compared to those in wild-type melanoma." (PMID 35069558, 2021). "The ectopic expression of miR-30b/30d has been reported to promote the metastasis of melanoma cells by directly targeting GALNT7 along with increasing the synthesis of immunosuppressive cytokine IL-10 while reducing the activation and recruitment of immune cells." (PMID 34819077, 2021). "However, within the melanoma model, IL-10 mRNA was clearly increased compared to RhS and detected in both epidermal keratinocytes, dermal fibroblasts, and melanoma nests (white arrows)." (PMID 32507967, 2020). "BRAFV600E mutant melanoma cells produce immunosuppressive factors such as IL-10, IL-6 or VEGF." (PMID 32054102, 2020). "As compared with H1299 control cells and similar to melanoma cells, CM from H1299 cells overexpressing bcl-2 promoted M2 polarization of M-DM, associated with increased expression of M2 (CD206, IL-10 and CCL1) and reduction of M1 (COX-2 and IL-12) markers and increased THP-1 cell migration." (PMID 32269145, 2020). "IFN-γ and IL-10 are two cytokines involved in the regulation of T cells activity, playing an opposite role, so we focused on their expression on PBMCs to evaluate a correlation with tumor response in advanced melanoma patients treated with anti-PD-1 drugs." (PMID 33077770, 2020). "In addition, pDCs in the melanoma environment drive a pro-inflammatory Th2 response and increase the frequencies of IL-5, IL-13 and IL-10 producing T cells." (PMID 32054102, 2020). "Our data suggest an interesting correlation between IFN-γ/IL-10 ratio and response to anti-PD-1 therapy in advanced melanoma patients, suggesting a new biomarker that could be easily incorporated in clinical practice." (PMID 33077770, 2020). "Recent study revealed that inhibiting the expression of GALNT7 in melanoma cells could decrease synthesis of immunosuppressive cytokine IL-10 and enhance immune cell activation and recruitment." (PMID 32308562, 2020). "Interestingly, also in human melanoma lesions, CD1a expression on DCs was reported to be decreased in metastatic lesions as compared to primary lesions, which coincided with IL-10 expression specifically in metastatic lesions." (PMID 32507967, 2020). "Although PBs have a potentially positive role in melanoma, the functional plasticity of these cells may result in transient switching to a “regulatory” pro-tumor phenotype owing to expression of TGFβ and IL-10 by this cell subset." (PMID 33569063, 2020). "Previous studies have shown that BRAF inhibition in melanoma cell lines resulted in a decreased secretion of immunosuppressive factors like IL-10, VEGF, and IL-6 and enhanced expression of melanocyte differentiation antigens (MDA) to improve recognition by MDA-specific T cells." (PMID 31541179, 2020). "In mice with melanoma, blockade of A2B receptors reduces IL-10, monocyte chemoattractant protein 1 (MCP-1), and MDSCs in the tumor site, which is associated with increased frequency of intratumoral CD8+ T cells, elevated levels of TNF-α and IFN-γ, and delayed tumor growth." (PMID 32793192, 2020). "In addition, IL-10 can exert anti-tumor activity in gliomas, melanomas, and brain and ovarian tumors, through a mechanism that involves the down-regulation of MHC-1, thus inducing cell lysis of tumor mediated by NK." (PMID 32283655, 2020).